IL33 (interleukin 33)
Diseases named in the same sentence as IL33 in open-access papers (continued):
Sharing a sentence is not in itself a finding about the gene and the disease.
breast cancer (continued). "We evaluated IL33 levels in two breast cancer cell lines and a normal cell line through WB and PCR techniques." (PMID 39911848, 2025). "In contrast, IL‐33 exhibits antitumor properties in B16 melanoma, 3LL, and 4 T1 mammary tumor models by enhancing the cytotoxicity and tumor infiltration of cytotoxic T cells and natural killer cells." (PMID 40751595, 2025). "This review systematizes current knowledge on the immunomodulatory effects of PD-1/PD-L1 and IL-33/ST2 signalling pathways in breast cancer antitumor immunity." (PMID 41284319, 2025). "Endogenous IL-33 mRNA level in mammary tumours showed significant time-dependent increase with the highest levels detected at day 28 after tumour challenge (fourfold increase in expression compared to the initial one)." (PMID 41284319, 2025). "The fact that its expression in tumour tissue correlates with cancer progression and prognosis shed a new light on the exploration of IL-33/ST2 signal pathway in breast cancer." (PMID 41284319, 2025). "Another article indicated that the MNK1/2-eIF4E axis supports immune evasion in postpartum breast cancer by regulating IL33 protein levels." (PMID 39755756, 2025). "This study investigated the involvement of the IL-33/sST2 axis in radiation-induced cardiac injury to provide potential novel targets for treating cardiac damage post-radiotherapy in breast cancer patients." (PMID 38585634, 2024). "Meanwhile, IL-33 and sST2 are important tumor development drivers and have been found to promote tumor metastasis in breast cancer." (PMID 38585634, 2024). "The levels of IL-33 and sST2 were elevated in patients with breast cancer, compared with the healthy control." (PMID 38585634, 2024). "A study involving 68 Brazilian women with breast cancer examined IL-33 expression across various subtypes and stages of the disease using quantitative polymerase chain reaction (qPCR)." (PMID 39125732, 2024). "Overexpression of IL-33 in B16 melanoma cells or 4T1 breast cancer cells highlighted the effect of IL-33 as a potent inhibitor of tumor progression, exerting its effects through the modulation of CD8+ T and NK cells." (PMID 38881897, 2024). "Expressions of IL-33 and sST2 were detected in breast cancer patients following radiotherapy, radiation-induced cardiac damaged mice model, and cardiomyocytes using quantitative real-time PCR (qRT-PCR) and immunohistochemical assay." (PMID 38585634, 2024). "The results revealed a significant upregulation of IL-33 in breast cancer tissues, particularly in the Triple-negative and Luminal B subtypes, compared to healthy controls." (PMID 39125732, 2024). "The results indicated that IL-33 and sST2 were highly expressed in breast cancer patients, which further elevated post-6 months but reduced after 12 months of radiotherapy." (PMID 38585634, 2024). "Pitavastatin also suppressed endogenous Il33 expression in PyMttg breast cancer cell line, which had high Il33 expression at baseline." (PMID 38816352, 2024). "It was found that the level of IL-33 in the GLM group was significantly higher than that in the group of breast cancer (BC) patients and the normal control group, but the level of sST2 in the GLM group was significantly lower than that in the BC group." (PMID 39148739, 2024). "The dual blockage of the PD-L/PD-1 and IL33/ST2 axes inhibited the progression of mice breast cancer." (PMID 37762328, 2023). "The complex role of IL-33 in the progression of breast cancer has gained significant attention, underscored by numerous patient-based studies." (PMID 37762328, 2023). "Promising antitumor achievements based on the blockade of the IL-33/ST2 axis were also determinate in breast cancer." (PMID 37762328, 2023). "In particular, it has been observed that individuals diagnosed with breast cancer typically present with considerably elevated serum levels of IL-33, suggesting a potential role for this cytokine as a biomarker for this malignancy." (PMID 37762328, 2023).
breast cancer (continued). "Inhibition of IL-33 led to impaired immune cell recruitment as well as type-2 immunity and suppressed breast cancer lung metastasis." (PMID 36635302, 2023). "This study not only sheds light on the intricate roles of IL-33 in breast cancer but also offers valuable insights for future IL-33-related research endeavors within this context." (PMID 38003516, 2023). "Our investigations have illustrated the IL-33/ST2 axis as a critical promoter of breast cancer proliferation and development by catalyzing the accrual of immunosuppressive cell populations within the tumor microenvironment." (PMID 37762328, 2023). "Our understanding of the IL-33/ST2 axis in breast cancer has come a long way, as we are uncovering its multifaceted roles in tumor growth, metastasis, and immunosuppression." (PMID 37762328, 2023). "For instance, CAFs promote lung metastasis of breast cancer by secreting interleukin (IL)-33 to mediate the immune microenvironment." (PMID 36635302, 2023). "These factors play essential roles in tissue remodeling and cell proliferation, thereby further implicating IL-33 and sST2 in the complex dynamics of breast cancer progression." (PMID 37762328, 2023). "By modulating both cancer cells and the anti-tumor immune response, IL-33 emerges as a promising therapeutic target in breast cancer immunotherapy." (PMID 37762328, 2023). "This review emphasizes the role of the IL-33/ST2 axis in breast cancer biology, its contribution to cancer progression and metastasis, its influence on the tumor microenvironment and cancer metabolism, and its potential as a therapeutic target." (PMID 37762328, 2023). "On the other hand, some evidences suggest that the application of IL-33 promotes metastasis and breast cancer growth." (PMID 37762328, 2023). "An investigation into a 4T1 breast cancer model revealed significantly higher IL-33 expression within tumor tissue, implying an immune response to 4T1 cells as a potential primary source of IL-33 in the tumor microenvironment." (PMID 37762328, 2023). "Interleukin-33 (IL-33), a member of the interleukin-1(IL-1) family of cytokines, remains poorly understood in the context of human breast cancer and its impact on treatment outcomes." (PMID 38003516, 2023). "IL33 facilitates immunosuppressive, and fibroblast-derived IL33 modifies the immune microenvironment to promote breast cancer growth and metastases." (PMID 37051596, 2023). "Several recent studies have ventured into understanding the implications of IL-33 and its soluble receptor, sST2, in the context of breast cancer." (PMID 37762328, 2023). "This study aimed to elucidate IL-33 expression patterns within tumor samples from a cohort of Brazilian female breast cancer patients undergoing neoadjuvant chemotherapy while exploring its correlation with clinicopathological markers." (PMID 38003516, 2023). "The IL-33/ST2 axis has been shown to have extensive pro-tumorigenic features in breast cancer, starting from tumor tissue proliferation and differentiation to modulating both cancer cells and anti-tumor immune response." (PMID 37762328, 2023). "IL-33 is engaged in the initiation and progression of many cancers like lung cancer, gastric cancer, bile duct cancer, breast cancer, and multiple myeloma." (PMID 37153553, 2023). "This review aims to dissect the emerging role of IL-33 within the framework of breast cancer, seeking to illuminate its potential implications on detection, prognosis, and treatment paradigms." (PMID 37762328, 2023). "In summary, IL-33 and its receptor sST2 hold promising potential as key players in the complex landscape of breast cancer progression and diagnosis." (PMID 37762328, 2023). "Elevated concentrations of IL-33 and sST2 have been identified in the serum of breast cancer patients in comparison to healthy individuals." (PMID 37762328, 2023). "The role of fibroblast-derived IL-33 in potentiating the occurrence of breast cancer metastases in the lungs was pointed out." (PMID 37762328, 2023).
breast cancer (continued). "The findings revealed a substantial upregulation of IL-33 expression in breast cancer patient samples, specifically within the Triple-negative and Luminal A and B subtypes, when compared to controls (healthy breast tissues)." (PMID 38003516, 2023). "It was demonstrated that elevated levels of IL-33 in the serum not only appeared in schizophrenia patients, but also indicated breast cancer recurrence." (PMID 37448488, 2023). "Collectively, these findings illuminate the multifaceted pro-tumorigenic role of IL-33 in breast carcinoma, impacting various aspects of the disease including the tumor tissue, cell proliferation and differentiation, metabolic processes, and immune responses." (PMID 37762328, 2023). "IL-33 enhances the migration and invasion of breast cancer, gastric cancer, colorectal cancer and lung cancer." (PMID 36110250, 2022). "Consistent with our idea, previous reports have shown that intratumor gene expression and the serum protein of IL-33 increased with primary tumor growth in the 4T1 breast cancer mouse model." (PMID 35805039, 2022). "Previous studies have shown elevated IL-33 plasma levels in lung cancer, breast cancer, gastric cancer, and advanced pancreatic ductal adenocarcinoma." (PMID 35409061, 2022). "On the other hand, exogenous IL-33 expression in aggressive melanoma and mammary tumour cell lines was found to inhibit xenograft tumour growth through infiltration of CD8+ T cells and NK cells." (PMID 35677533, 2022). "The induction of Th2-driven airway inflammation with either IL-33 or Aspergillus protease allergen was recently shown to increase experimental lung metastasis by B16 melanoma and spontaneous lung metastasis by 4T1 mammary carcinoma cells." (PMID 35756626, 2022). "We found that IL-33 levels were positively correlated with LPIN1 levels in breast cancer tissues, indicating that the IL-33 facilitates breast carcinogenesis via enhanced LPIN1 expression." (PMID 33946554, 2021). "We observed that COT-JNK is a critical signal transducer for the regulation of LPIN1 expression by IL-33 induction in breast cancer cells." (PMID 33946554, 2021). "Another study claimed that IL-33 was used as a target for patients with treatment-resistant breast cancer via the attenuation of epithelial–mesenchymal transition and cancer stemness." (PMID 34298657, 2021). "Modulation of the levels of IL-33 in breast cancer by exogenously administered IL-33 resulted in the promotion of tumor growth and metastasis." (PMID 34209038, 2021). "In a mouse model for breast cancer and pulmonary metastasis, endogenous IL-33 was elevated at both mRNA and protein levels in a time-dependent manner during cancer progression." (PMID 34209038, 2021). "Previous studies have reported that ILs such as IL-17A, IL-22, and IL-33 promote neoplastic cell transformation and breast cancer tumorigenesis." (PMID 33800170, 2021). "In a mouse model of breast cancer, tumor progression is associated with an increase of endogenous IL-33 and this cytokine promoted a significant rise in the amount of TGF-β-producing MDSCs within the mammary tumor." (PMID 31948072, 2020). "In a breast cancer model, IL-33 administration increased the percentage of NKp461+ PD-1+ cells in the TME, while these cells were less frequent in ST2-deficient mice." (PMID 33329534, 2020). "In a breast cancer model, IL-33 induced the recruitment and activation of NK cells to the lung that prevented pulmonary metastasis onset." (PMID 33329534, 2020). "IL-33 is overexpressed in various cancers and the serum concentration of IL-33 is a valuable indicator of poor prognosis in breast cancer." (PMID 32854705, 2020). "In contrast with these studies, investigations performed in breast cancer model demonstrated that IL-33/ST2 alters NK cell activation." (PMID 31652497, 2019). "Another study pointed that high IL33 value in 4T1 breast cancer cells reduces tumor growth and metastasis in vivo." (PMID 31781173, 2019).
breast cancer (continued). "In a subsequent study, administration of exogenous IL-33 to breast cancer-bearing mice was seen to enhance tumor growth and metastasis." (PMID 31231372, 2019). "In allogeneic transplantation and tumor environments, it has been shown that IL-33 can induce MDSCs expansion, which inhibits transplant rejection and promotes the progression of mouse breast cancer through inhibition of T cell responses." (PMID 30863362, 2019). "IL-33 levels were demonstrated to be a positive prognostic marker in hepatocellular carcinoma and in breast cancer cells." (PMID 31652497, 2019). "IL-33 and ST2 are both elevated in comparison to adjacent healthy tissue in breast cancer, with serum levels of IL-33 and its decoy receptor soluble ST2 (sST2) also elevated." (PMID 31231372, 2019). "More precisely, in this model they found that ILC2s trigger tumor progression and metastasis development in response to IL-33, sustaining the immunosuppressive milieu that characterizes breast cancer patients." (PMID 31849977, 2019). "Much of the early work examining IL-33 in tumorigenesis focussed on the role of IL-33 in breast cancer." (PMID 31231372, 2019). "It was previously reported that exogenous IL-33 enhances accumulation of MDSCs both in murine mammary tumor and spleen." (PMID 30001716, 2018). "Expression of IL-33 was found to stimulate the recruitment of M2-like macrophages into the cancer microenvironment in mouse models of colon and breast cancer correlating with tumor progression." (PMID 30483263, 2018). "IL-33 released in tumor tissues in breast and colorectal cancer mouse models and in breast cancer patients, has been shown to facilitate MDSC expansion, recruitment and survival in the TME." (PMID 30416507, 2018). "Recent study showed that IL-33 promotes breast cancer growth andmetastases by amplification of ST2L+Treg cell populations in a model of breast cancer, which supported our findings." (PMID 29950152, 2018). "IL-33/ST2 axis promoted breast cancer growth and metastases by facilitating intratumoral accumulation of immunosuppressive and innate lymphoid cells." (PMID 29568370, 2018). "Analysis of the clinical data shows that expression levels of IL-33 are reduced during tumor progression in breast cancer and inversely correlate with tumor grade." (PMID 29499051, 2018). "In contrast with these reports, previous studies in 4T1 breast cancer model showed that IL-33/ST2 signaling impairs NK cell activation." (PMID 30483263, 2018). "Recently, studies have shown that IL-33 also has antitumor activity in some cancers, such as melanoma and breast cancer." (PMID 29896199, 2018). "Consistent with these mouse data, IL-33 has been shown to be reduced in many epithelial cancer cells including breast cancer, colorectal cancer and cervical cancer." (PMID 29499051, 2018). "In women, IL-33 highly promotes epithelial cell proliferation and tumorigenesis in breast cancer, since IL-33 increases Cancer Osaka Thyroid (COT) phosphorylation via ST2-COT interaction in normal epithelial and breast cancer cells." (PMID 30416507, 2018). "In summary, the IL-33/ST2 pathway promotes progression of breast cancer in both pre-clinical and clinical studies mostly through the recruitment of inflammatory cells that enhance tumor growth, invasiveness, and angiogenesis." (PMID 30205617, 2018). "Histological examination of tissues from these patients showed higher IL-33 expression in breast carcinomas as compared to tumor-adjacent normal tissues." (PMID 30205617, 2018). "In breast cancer patients, serum levels of IL-33 and of its decoy receptor sST2 were enhanced compared to healthy controls." (PMID 28119694, 2016). "In 4T1 breast cancer model mice, intraperitoneal administration of IL-33 promoted tumour angiogenesis through facilitating the intratumoural accumulation of immunosuppressive and innate lymphoid cells; this process was attenuated in ST2-deficient mice." (PMID 27882929, 2016).
breast cancer (continued). "Next, we analyzed the association of IL-33, IL-33R and VEGF expression with MVD in perinecrotic breast cancer tissue." (PMID 26919112, 2016). "In mammary tumor cells both IL-33 and IL-33R expression positively correlated with VEGF expression (r = 0.375; p = 0.017; r = 0.292; p = 0.038, respectively)." (PMID 26919112, 2016). "Taking together, our data indicate that IL-33/IL-33R pathway is critically involved in mammary tumor growth by facilitating expression of pro-angiogenic VEGF in tumor cells and attenuating tumor necrosis." (PMID 26919112, 2016). "In this study, we show that deletion of a receptor for immunoregulatory IL-33 promotes mammary tumor necrosis in mice." (PMID 26919112, 2016). "In breast cancer, the IL-33/ST2 pathway has been found to accelerate cancer progression via enhanced intratumoral accumulation of immunosuppressive cells, and by the suppression of innate antitumor immunity." (PMID 27074834, 2016). "Expression of IL-33 is positively associated with VEGF expression, in animal and human breast cancer cells." (PMID 26919112, 2016). "The IL-33/ST2L axis promoted tumour progression in a breast cancer mouse model by diminishing innate anti-tumour immunity resulting from the accumulation of immunosuppressive cells." (PMID 27882929, 2016). "Deletion of IL-33R (ST2) gene in BALB/c mice enhanced tumor necrosis and attenuated tumor growth in 4T1 breast cancer model, which was associated with markedly decreased expression of vascular endothelial growth factor (VEGF) and IL-33 in mammary tumor cells." (PMID 26919112, 2016). "In the 4T1 breast cancer model, IL-33 was expressed by CD45-positive leukocytes and tumor cells, while ST2 was mainly expressed on Tregs and type-2 ILCs." (PMID 28119694, 2016). "Our findings reveal a novel role for IL-33/IL-33R pathway in breast cancer neoangiogenesis and necrosis." (PMID 26919112, 2016). "We have previously shown that deletion of IL-33/IL-33R axis facilitated anti-tumor immunity which led to attenuated tumor growth and metastasis in experimental mammary carcinoma." (PMID 26919112, 2016). "Here, we found that the serum levels of IL-33 and sST2 were higher in patients with breast cancer than in healthy volunteers, suggesting that IL-33 and sST2 were associated with this disease." (PMID 26456994, 2015). "IL-33 and sST2 were significantly associated with MMP-11 or PDGF-C which indicated poor prognosis of breast cancer patients." (PMID 26456994, 2015). "Here, our ELISA data showed an elevation of MMP-11 in sera of breast cancer patients and a significant association between MMP-11 and IL-33 or sST2 concentration was found." (PMID 26456994, 2015). "Here, the serum levels of Interleukin-33 (IL-33) and sST2 were found significantly higher in breast cancer patients than in healthy volunteers." (PMID 26456994, 2015). "Sera concentration of IL-33 and sST2 was significantly higher in patients with breast cancer than in healthy volunteers (IL-33: 200.20 ± 9.35 pg/mL versus 16.34 ± 0.68 pg/mL, sST2: 104.30 ± 4.54 pg/mL versus 26.13 ± 1.20 pg/mL)." (PMID 26456994, 2015). "The percentage of IL-33-positive tissue in breast tumors, tumor-adjacent tissues, and normal tissues from breast cancer patients." (PMID 24778632, 2014). "We found that serum levels of IL-33 and sST2 in breast cancer patients were significantly higher than in healthy women." (PMID 24636276, 2014). "The present study found for the first time that serum levels of IL-33 and sST2 in breast cancer patients had significant correlations with VEGF." (PMID 24636276, 2014). "In studies on mouse mammary carcinoma, the IL-33/ST2 pathway promotes BC progression and metastasis through increased intratumoral accumulation of immunosuppressive cells and by diminishing innate anti-tumor immunity." (PMID 24778632, 2014). "This hints at a role of IL-33/ST2 signaling in the Th2 polarization of immune response in the breast cancer model." (PMID 21484786, 2011).